TNF (tumor necrosis factor)
Diseases named in the same sentence as TNF in open-access papers (continued):
Sharing a sentence is not in itself a finding about the gene and the disease.
tumor (continued). "The authors found a reduction in TNF-α expression of about 50% that may be further investigated, since TNF-α can act as an endogenous cancer promoter, bridging inflammation and carcinogenesis, and it has been found to be highly expressed in different preneoplastic and tumor tissues." (PMID 39861072, 2024). "Furthermore, the classification between the non-tumor and the tumor groups could be more correctly predicted by including information of Vpr and anti-Vpr IgG into age, CD4, CD8, HIV viremia, HBV, viremia, HCV viremia, IL-6, and TNFα." (PMID 38166062, 2024). "Moreover, TNF-α and IFN-γ could induce high levels of CD40 on mature MDSCs through interacting with CD40L on T cells after CTT to promote Th1-dominant CD4+ T cell differentiation and orchestrate CTT-induced long-term anti-tumor immunity." (PMID 38791188, 2024). "Furthermore, the serum levels of tumor necrosis factor α (TNF‐α), interleukin‐2 (IL‐2), and interferon‐γ (IFN‐γ) were significantly increased in SW1990‐loaded mice, suggesting that SD may exert anti‐tumor activity by stimulating the immune function of the body." (PMID 39155844, 2024). "Moreover, additional groups of tumor‐bearing mice received intraperitoneal CDDP (1 mg/kg) administration along with the vector at days 0, 4, 7, 11, and 14 post vector treatment in order to investigate the effects of combination of chemotherapy and TNFα gene therapy, chemovirotherapy." (PMID 37331004, 2023). "Immunohistochemical analysis of morphologically intact tumor cells at the junction of histotripsy ablated and non-ablated zones demonstrated rapid and transient colocalized upregulation of pRIPK3 and pMLKL indicating the onset of necroptosis, a TNFα-driven pathway of immunogenic cell death." (PMID 36756111, 2023). "Importantly, IFN-γ+TNF-α+ CD8+ T cells were not present in unstimulated splenocytes from CR mice (CR No Stim) or in stimulated splenocytes from tumor-naive control mice (Naive + AH1), indicating the presence of a tumor antigen–specific CD8+ T cell memory pool in spleens of CR mice." (PMID 36810257, 2023). "We also found TNF-α could upregulate HLA-E protein expression in tumor cells (data was not shown)." (PMID 38007483, 2023). "However, treatment of ITF2357, I‐BET151, or JQ1 only on T cells directly isolated from the OT‐I mouse spleen did not increase the secretion levels of IFNγ, GZMB, or TNFα, suggesting the drug effects are dependent on the interaction of T cells with the tumor or other stroma cells in the organoids." (PMID 37271874, 2023). "Further studies are required to investigate if TNF-α or IL-1RA may be playing a role in metastasis in early-stage OGJ patients and whether targeting these soluble factors might prevent metastatic dissemination in OGJ patients or prevent tumour progression to more advanced stages." (PMID 36790524, 2023). "Similarly, other factors released by tumor cells, such as the platelet-derived growth factor (PDGF) and fibroblast growth factor 2 (FGF-2), or inflammatory signals such as interleukin (IL)-1, IL-6 and tumor necrosis factor alpha (TNF-α), recruit and proliferate additional CAFs." (PMID 37173977, 2023). "In further support to the upregulation of key effectors for tumour surveillance, lepadin A increased synthesis of IL-6 and reduced the secretion of the immunosuppressive cytokine IL-10 in the supernatants of the co-cultures with DCs, while did not affect the levels of IL-1β and TNFα." (PMID 37779162, 2023).
tumor (continued). "Unlike propofol, sevoflurane exposure resulted in bigger tumour size, shorter survival time (assessed with the clinical endpoints, including body weight loss > 20% and tumour volume > 70 mm3), higher HGF, HIF1α, IL1β and TNFα expressions, and lower E-cadherin and TIMP-2 expressions." (PMID 35953652, 2023). "TNF-alpha signaling via NF-kB, IL6/JAK/STAT3 signaling, PI3K/AKT/mTOR signaling, MYC targets v2, TGF-beta signaling, and Kras signaling were mostly negatively correlated with LRRC3B expression, consistent with silencing of LRRC3B in tumor tissue, which may result in carcinogenesis." (PMID 36798137, 2023). "Similarly, CSC expressing high levels of CD44 were found to significantly elevate TNF-α secretion along with other inflammatory cytokines such as Interleukins (IL-1beta, IL-10, IL-12) and angiogenic factors (Angiopoietin-1 & 2, VEGF, and bFGF) owing to increased oral tumor stemness." (PMID 38170015, 2023). "In particular, oestrogens may favour an immunosuppressive TME by enhancing Th2 responses, tumour-promoting cytokines (IL-4, IL-6, IL-17A and TNF) and M2 TAM infiltrations, unlike M1 TAM infiltration and Th1 responses, which are commonly joined with Th1 cytokines (IL-12 and IFN)." (PMID 38332913, 2023). "Also, chrysin has been found to reduce EAC tumor size through inhibiting VEGF and inflammatory molecules involved in angiogenesis, suppressing DNA topoisomerases, and histone deacetylase, as well as downregulating tumor necrosis factor α (TNF-α) and interleukin 1β (IL-1β)." (PMID 36905557, 2023). "Moreover, there are many growth factors involved in tumor angiogenesis, such as vascular endothelial growth factor (VEGF), epidermal growth factor (EGF), angiogenin (Ang), fibroblast growth factor (FGF), platelet-derived growth factor (PDGF), TNF-α and placental growth factor (PLGF)." (PMID 38298540, 2023). "Furthermore, chronic tumor exposure had a negative impact on general NK-cell anti-tumor function, resulting in reduced degranulation and decreased expression of effector cytokines IFNγ and TNFα in NK cells exposed to tumors and re-challenged with either PVR+ and PVR− K562 cells." (PMID 37345049, 2023). "Moreover, inflammatory cytokines secreted by the tumor, such as TGF-β, TNF-α, IL-1, IL-6, IL-8, and IL-10, could induce local inflammation and fibrosis, which affect the electrophysiological characteristics of adjacent myocardium of pulmonary veins and atrium, facilitating occurrence of AF." (PMID 37519821, 2023). "Furthermore, IL-2, IL-12, IFN-γ and TNF-α have been reported to stimulate CD4+ Th1 differentiation and accelerate Th1-mediated antitumor responses; In addition, these cytokines stimulate CD8+ cytotoxic T lymphocytes (CTLs), the most important effector cells that recognize and eliminate tumor cells." (PMID 37048096, 2023). "Moreover, TNF-α could upregulate p-AKT and p-ERK expressions in tumor tissues." (PMID 37124061, 2023). "Thus, we assume that in contrast to the luminal cell line MCF-7, TNBC cells can activate the endothelium through endogenous expression and secretion of proinflammatory factors, thereby leading to an efficient tumor cell adhesion, even in the absence of exogenous TNFα." (PMID 35163822, 2022). "In addition, TNF members could activate immunosuppressive cells (regulatory T cells and myeloid-derived suppressor cells) through TNF receptor 2 (TNFR2), thus supporting immune escape and promoting tumor cell proliferation." (PMID 35000592, 2022). "MHC class I-restricted CD8+ cytotoxic T lymphocytes (CTLs) could initiate tumor cell apoptosis by secreting cytotoxic granules containing perforin and granzyme, or indirectly kill cancer cells by secreting cytokines such as IFN-γ and tumor necrosis factor (TNF)." (PMID 36505462, 2022).
tumor (continued). "Adipocytes and their precursor cells can influence tumor behavior via various hormones, growth factors, and cytokines known as adipokines including leptin, adiponectin, IL-6, hepatocyte growth factor, autotaxin, and TNF-alpha although their exact mechanism of action has not been established." (PMID 34532758, 2022). "However, inflammatory cells produce tumor necrosis factor-α, transforming growth factor-β, interleukin-6 (IL-6), and other cytokines, which regulate the transcription factor NF-κB and the signal transducer and activator of transcription-3 (STAT3) pathways, and promote tumor cell metastasis." (PMID 36686786, 2022). "Furthermore, NK cells secrete pro-inflammatory cytokines and chemokines (such as IFN-γ, TNF-α, IL-6, granulocyte–macrophage colony-stimulating factor (GM-CSF) and CCL5) that might exert direct anti-tumor activity in addition to promoting innate and adaptive responses." (PMID 35759090, 2022). "The negative correlation observed in E0771 tumors between TNF-α expression on day 12 and granzyme B on day six indicates that the cell-mediated (i.e., Th1) response is transient and not sustained by day 12 when physical changes in tumor volume due to IMT were noted." (PMID 35214172, 2022). "While infliximab and adalimumab are based on anti-TNF antibodies and bind only to TNF, etanercept is based on a TNFR-2-Ig fusion protein that can bind TNF and LTα, which could have consequences, since LTα potentially has a TNF-independent role in tumor control." (PMID 36358688, 2022). "In addition, the immunosuppressive tumor microenvironment of CT26-Luc tumor was distinctly relieved under the effect of BMS202, as characterized by increased infiltration of CD8+ T cells in tumors and enhanced secretion of antitumour cytokines (IFN-γ and TNF-α)." (PMID 33935796, 2021). "TNFSF10 and BCL2L1 were other selected genes that were considered expression-driven dependency genes 4, and TNFSF10 belonged to the family of tumor necrosis factor (TNF) ligands that could induce apoptosis in tumor cells but normally did not kill healthy cells." (PMID 33850477, 2021). "Thus, our results suggest that immunotherapeutic approaches should aim to augment TNFα rather than IFNγ in the tumor microenvironment, and that MSCs may be a barrier to stimulating effector cells within the tumor microenvironment." (PMID 34869307, 2021). "However, following ex vivo stimulation with SIINFEKL peptide IFN-γ, TNF-α nor IL-2 production was increased in combination treated mice spleen but not tumor compartment, suggesting that antigen-specific CD4 T cells reside prevalently in secondary lymphoid organ." (PMID 34276686, 2021). "Finally, since multiple soluble mediators, such as TNF-α, IFN-γ, IL-1β, IL-17, and IL-27, induce PD-L1 expression on tumor cells, it may be reasonable to raise the question of whether the expression of certain mediators among them is downregulated by NDRG2 expression." (PMID 34885221, 2021). "Indeed, the tumor nodules were characterized by diminished levels of inflammatory cytokines IFNγ and TNFα when compared to non-tumoral tissue, while the intratumoral frequency of Treg was enhanced, which is classically associated with HCC progression and poor survival." (PMID 34638465, 2021). "Furthermore, we observed that RRx-001 treated RBCs demonstrated increased adhesive potential to endothelial cells upon introduction of TNF-α and hypoxia, both of which increase endothelial PSR expression, suggesting that that the compound may induce preferential adhesion in the tumor." (PMID 33946824, 2021). "In addition, T cells are the primary cell type in tumor immunity; among them, CD4+ subtypes could modulate the anti-tumor immunity via secreting cytokines, while CD8+ subtypes could conduct the secretion of specific inhibitory cytokines, including IFN-γ and TNF-α." (PMID 33435880, 2021).
tumor (continued). "In addition, Ciji-Hua’ai-Baosheng improved the immune function of H-22 tumor-bearing mice after treatment with chemotherapy and alleviated CTX-induced colitis, manifested as elevated lymphocytes in spleen, augmented IL-2, IFN-γ and TNF-α, and the reduced IL-6 in serum and tumor tissues." (PMID 34722304, 2021). "Hence, CAR-NK-92 cells exert its tumor killing mainly through (i) granule-mediated cytotoxicity via perforin and granzymes; (ii) death receptor-mediated apoptosis, involving FasL and TRAIL; and (iii) the secretion of proinflammatory cytokines and chemokines, e.g., TNF-α, IFN-Ɣ, and CCL3." (PMID 34337077, 2021). "Furthermore, IFN-γ/IL-2 profile of cytokine production (without TNF-α) could be ascribed to regulatory T cells that suppress the anti-tumor functions of CD4 +, CD8 +, and NK cells, leading to an absence of effective anti-tumor immune response." (PMID 34199989, 2021). "Moreover, we observed specific TNFα-induced apoptosis of ERα-positive cells, consistently with our previous report, and we further confirmed that knockdown of NCOR1 and TNFα treatment exerted a similar targeted apoptosis-inducing effect in vitro and tumor growth inhibition in vivo." (PMID 34073371, 2021). "However, what about a tumor context in which no TNFR2 signal is delivered because TNF-α is absent?" (PMID 34712661, 2021). "Hence, re‐sensitising cancer cells to TNF‐mediated bystander killing might be a potent mechanism to kill antigen‐negative tumour cells." (PMID 32419365, 2020). "Furthermore, antibody-mediated depletion of TGF-βi led to reduced tumour burden in spontaneously developing murine models of PDAC and critically, these tumours were more highly infiltrated with CD8+ T cells that expressed greater levels of granzyme B, IFNγ and TNFα." (PMID 32967079, 2020). "Also, treatment of CXCL9 could dose-dependently reduced the mRNA expression and secretion of anti-tumour cytokines from CD8+ cytotoxic T cells, including TNFα, IL2, and IFNγ, further proving that CXCL9 treatment could lead to cytotoxic T cell exhaustion and dysfunction." (PMID 31913856, 2020). "In addition, TLR-L and/or Zol-treated pDCs elicited production of IFNγ and TNFα in cocultures and stimulated the cytotoxic activity of γδ T cells as illustrated by the upregulation of CD107 surface expression and secretion of perforin following culture with tumor cells." (PMID 32435249, 2020). "Altogether these findings suggest that M0 macrophage-secreted TNF-α is a robust anti-tumor cytokine, but that exposure of macrophages to tumor microenvironmental cues functions to convert macrophages into subsets that no longer express sufficient TNF-α to exert anti-tumor activities." (PMID 33267818, 2020). "Additionally, tumor cells are capable of producing mediators of chronic inflammation, such as granulocyte-macrophage colony-stimulating factor (GM-CSF), vascular endothelial growth factor (VEGF), TNF-α, IL-1β, and IL-6, which induce the generation and expansion of MDSCs in situ." (PMID 33042814, 2020). "Thus, it is expected that treatment with ICA-Cubs has a greater potential to reduce the production of TNF-α within the cytosol of the SKOV-3 cells, and this could interfere with angiogenesis in the tumor microenvironment and the growth, proliferation, invasion, and metastasis of cancer cells." (PMID 33374293, 2020). "However, it seems that some of the well-defined proinflammatory cytokines such as TNFα, IL-1β, and IL-6 may not play the role as the expression of these cytokines were remarkably downregulated in tumor tissues." (PMID 32382012, 2020). "However, following stimulation by TNFα, the equilibrium between the two cell types was changed: not only the tumor cells but also MSCs - although at lower levels - contributed to the elevation in CXCL8 expression by the cytokine-stimulated co-cultures (Figure 3A2)." (PMID 31105691, 2019).
tumor (continued). "Interestingly, the results showed that the IFNγ, TNFα, and IL-6 levels in the serum of the CAR-147 macrophage group were decreased compared with that of the control group, while the IL-12 and IFNγ levels were increased in tumour tissue samples from the CAR-147 macrophage-treated mice." (PMID 31570753, 2019). "Moreover, it is well known that many cytokines, such as TNF-α, COX2, and IL6, can regulate carcinogenesis by affecting cell proliferation and apoptosis; thus, the production of cytokines was examined by quantitative real-time PCR (qRT-PCR) in the tumor tissues of Ct55 knockout and WT mice." (PMID 30944312, 2019). "This TNFα/MCP-1 cascade is consistent with the infiltration of macrophages into tumours in at least two in vivo models of cancer, and may point to IgE-mediated mobilisation and activation of monocytes/macrophages into tumours by promoting TNFα-induced production of MCP-1 in the TME." (PMID 31544825, 2019). "Nine hallmarks could be related to tumor immunology and collectively showed a decreased expression over time (allograft rejection, complement, IL2-STAT5 signaling, IL-6-JAK-STAT3 signaling, inflammatory response, IFN-α response, IFN-γ response, KRAS signaling up, and TNF-α signaling via NF-κB)." (PMID 31921184, 2019). "It is also possible that, because CCL5 is sufficient but not necessary for tumor recurrence, it would be preferable to block the induction of the pro-inflammatory program that is induced following Her2 downregulation using agents targeting TNFα or the NFκB pathway." (PMID 30990165, 2019). "Thus, the TNF-inducible expression of CSPG4 in combination with TNF elaborated from CSPG4-CAR-T cells may create a feed-forward loop culminating in uniform CSPG4 expression on GBM cells, paving the way for complete tumor eradication." (PMID 31779130, 2019). "Interestingly, this in vivo NF-κB response of KRASMUT cells was abolished in IL-1β-deficient (Il1b−/−31), but not in TNF-deficient (Tnf−/−32), mice, indicating that KRASMUT tumor cells selectively respond to IL-1β of the pleural environment by activating NF-κB." (PMID 29445180, 2018). "Predomination of proinflammatory TNF-α/IFN-γ-producing Th1 cells, besides enhancing CTL activity, also facilitates innate antitumor mechanisms and associates with the absence of metastatic invasion, tumor recurrence, and increased survival of patients with CRC." (PMID 29849497, 2018). "Interestingly, the IL‐12‐producing CAR‐T cells can also inhibit tumour growth of CEA‐negative MC38 cells when these cancer cells are co‐injected with CEA‐positive C15A3 cells, and such suppressive effects disappear with anti‐TNF‐α‐neutralizing antibody treatment." (PMID 29963704, 2018). "Similar to other natural compounds, taxanes have been reported to display anti-tumor effects that are not directly related to microtubule stabilization, but results from enhanced phosphorylation of Bcl-2, release of tumor necrosis factor-α (TNF-α) and a decrease in expression of TNF receptors." (PMID 30459936, 2018). "Moreover, in the current study patients with ≥5 CTCs exhibited significant impairment in the ability of TLR-activated mDCs to secrete TNF-α and IL-12, potentially leading to an absent or reduced Th1-like response, similar to that observed in tumor microenvironment with myeloid-derived cells." (PMID 27374101, 2017). "Because FADD absence did not affect TNF-mediated cytokine secretion, and CD95L did not induce the secretion of cytokines from 3LL cells, it is unlikely that these death ligands are responsible for the decreased tumor burden observed in the syngeneic FADD-deficient 3LL model." (PMID 28212753, 2017). "Although we did not again examined the shedding status of TNF-α in mouse stomach in the present study, the remarkable suppressive effect of Nrdc deletion on inflammation may lead to the suppression of metaplastic changes and tumor formation." (PMID 28230087, 2017).